PPP1R3C (protein phosphatase 1 regulatory subunit 3C)
Description:
Acts as a glycogen-targeting subunit for PP1 and regulates its activity. Activates glycogen synthase, reduces glycogen phosphorylase activity and limits glycogen breakdown. Dramatically increases basal and insulin-stimulated glycogen synthesis upon overexpression in a variety of cell types.
Synonyms: PTG; PPP1R5
Tractability: Antibody: the Human Protein Atlas places it where antibodies can reach. PROTAC: UniProt records ubiquitination sites on it; ubiquitination databases record sites on it.
Gene: Protein-coding gene on chromosome 10 (91,628,442 to 91,633,071, reverse strand). Ensembl gene ENSG00000119938.
Subcellular location (Human Protein Atlas): Cytosol; Nucleoplasm; Plasma membrane
Pathways (Reactome):
Disease: Myoclonic epilepsy of Lafora
Metabolism: Glycogen synthesis
Gene Ontology:
Molecular function: protein binding; protein-macromolecule adaptor activity; glycogen binding; protein phosphatase 1 binding; protein phosphatase binding; protein serine/threonine phosphatase activity; molecular adaptor activity
Biological process: glycogen biosynthetic process; glycogen metabolic process; regulation of glycogen biosynthetic process
Cellular component: cytosol; protein phosphatase type 1 complex
Genetic constraint (gnomAD): Loss-of-function variants: 20 observed, 30.74 expected, observed/expected ratio (o/e) 0.65, 90% interval 0.46 to 0.94. The upper end of that interval is the gene's LOEUF score, 0.94, which puts it in group 4 of 6, group 1 being the genes least tolerant of losing a copy. Missense variants: 321 observed, 406.03 expected, observed/expected ratio (o/e) 0.79, 90% interval 0.72 to 0.87. Synonymous variants: 123 observed, 150.59 expected, observed/expected ratio (o/e) 0.82, 90% interval 0.7 to 0.95.
Homologues: Orthologues: chimpanzee PPP1R3C (99% identical), macaque PPP1R3C (97% identical), rabbit PPP1R3C (91% identical), dog PPP1R3C (91% identical), pig PPP1R3C (89% identical), guinea pig PPP1R3C (88% identical), mouse Ppp1r3c (86% identical), rat Ppp1r3c (84% identical), tropical clawed frog ppp1r3c (59% identical), zebrafish ppp1r3cb (54% identical), zebrafish ppp1r3ca (46% identical), Drosophila melanogaster Gbs-70E (32% identical), and 1 more. Paralogues in human: PPP1R3B (38% identical), PPP1R3A (23% identical), PPP1R3D (21% identical), PPP1R3G (19% identical), PPP1R3F (18% identical), PPP1R3E (16% identical).
Diseases named in the same sentence as PPP1R3C in open-access papers:
PPP1R3C is named in the same sentence as 34 diseases in open-access papers, as found by Europe PMC text mining. Sharing a sentence is not in itself a finding about the gene and the disease. The quoted sentences say what the papers report.
cervical cancer (6 papers, 2015 to 2025). A primary or metastatic malignant neoplasm involving the cervix. "In cancer, PPP1R3C is reported to act as a tumor suppressor, and to be highly methylated in cervical cancer and melanoma, thus resulting in cancer cell proliferation associated with high glucose levels in blood." (PMID 37511212, 2023). "Only one of the downregulated genes in the tumor tissues, PPP1R3C, had previously been reported to be downregulated in cervical cancer." (PMID 25789025, 2015). "Based on the findings of a previous study, the PPP1R3C gene is downregulated in cervical cancer; its methylation status has been reported in melanoma, colon and prostate cancers, but not in cervical cancer." (PMID 25789025, 2015). "From these results, the expression of the CAMK2N1, ALDH1A3 and PPP1R3C genes are were shown to be suppressed in cervical cancers by DNA methylation." (PMID 25789025, 2015). "Similar to the present results, the PPP1R3C gene is highly downregulated in cervical cancer, as per the GENT database." (PMID 25789025, 2015). "During the progression of cervical cancer, from normal cervical tissues to CIN 1, 2 and 3, the gradually down‐regulated genes we confirmed were CRISP3, CRISP2, PPP1R3C, and DSG1." (PMID 33624385, 2021). "Many researchers have shown that PPP1R3C, PPKAR2B and AKT3 may play important roles in cervical cancer, cardiovascular events and prostate cancer." (PMID 33176720, 2020). "Two other genes, PPP1R3C and CAMK2N1, were downregulated by hypermethylation in cervical cancer." (PMID 25789025, 2015).
colorectal cancer (5 papers, 2014 to 2025). A primary or metastatic malignant neoplasm that affects the colon or rectum. "The protein phosphatase 1 regulatory subunit 3C (PPP1R3C) modulates glycogen metabolism, and methylation of the PPP1R3C gene has been proposed to play a critical role in colorectal cancer." (PMID 33030559, 2021). "Takane et al25 found the aberrant promoter methylation of PPP1R3C and EFHD1 in plasma of colorectal cancer (CRC) patients, and verified that both of them could be potential detection markers for CRC." (PMID 30039914, 2018).
Insulin resistance (5 papers, 2021 to 2025). Increased resistance towards insulin, that is, diminished effectiveness of insulin in reducing blood glucose levels. "Nevertheless, previous findings demonstrated that mice with a heterozygous deletion of PPP1R3C have reduced glycogen stores in the heart and develop progressive glucose intolerance and insulin resistance with aging." (PMID 34722683, 2021). "The KEGG pathway analysis indicated that the upregulated DEGs were significantly enriched in insulin resistance, which included PPP1R3A and PPP1R3C." (PMID 35499169, 2022). "The DEGs and DELs between the QGL and MOD groups, such as TG, SIK1, PPP1R3C, CRTC2, PGC-1α, G6PC, PPP1R3G, and SREBP1 were found to be relevant to insulin resistance." (PMID 36452137, 2022). "Our research indicated that QGD may improve insulin resistance via regulating the expression of CRTC2, SIK1, PPP1R3C, PGC-1α, G6PC, PPP1R3G, and SREBP1, which are involved in gluconeogenesis." (PMID 36452137, 2022). "In addition to modulating gluconeogenesis and insulin resistance and thus indirectly influencing SREBP1 activity, both SIK1 and PPP1R3C can directly regulate SREBP1 expression." (PMID 36452137, 2022).
melanoma (4 papers, 2011 to 2023). A malignant, usually aggressive tumor composed of atypical, neoplastic melanocytes. "Concerning melanoma, this data is also confirmed in TCGA, where a lower expression of PPP1R3C is related to a worse overall survival." (PMID 37511212, 2023). "We analyzed a few of the top DEGs (NRP2, CAPN3, DMBT1, BRAF, DDIT3, PPP1R3C, NF1) using The UCSC Xena platform that has large number of RNA-seq data of normal tissue from healthy individuals (GTEx) and primary tumor and metastatic tissue data from melanoma patients (TCGA)." (PMID 32983966, 2020). "We identified four genes, PPP1R3C, ENC1, RARRES1 and TP53INP1 that were not previously known to be silenced by DNA methylation in melanoma." (PMID 22028813, 2011).
breast carcinoma (3 papers, 2014 to 2023). "Previous studies have proposed that glycogen accumulation in breast cancer cells is due to HIF1α mediated increase in GYS1 and/or PPP1R3C expression in hypoxia." (PMID 31536495, 2019).
Obesity (3 papers, 2012 to 2023). Accumulation of substantial excess body fat. "Ppp1r3c is enriched in adipocytes and is noteworthy that it increases during the browning process and Cyp2b10 is known to be regulated by nuclear receptors like PXR, repression of which leads to obesity and exacerbation of metabolic disease by disrupting metabolism of fatty acids." (PMID 36967237, 2023).
colon cancer (2 papers, 2021 to 2023). "PPP1R3C (PTG, Gene ID: 5507) is highly methylated in colon cancer and is a feature of colon cancer epigenetics, which may play an important role in tumor cell growth associated with blood glucose levels." (PMID 33624385, 2021).
serous ovarian cancer (2 papers, 2023 to 2024). "Remarkably, we identified a potential prognostic role of AhRR and PPP1R3C in serous ovarian cancer by bioinformatics analyses of array-CGH data performed on these CSCs." (PMID 39596687, 2024). "In conclusion, we reported for the first time, to the best of our knowledge, the prognostic role of AhRR and PPP1R3C expression in serous ovarian cancer, and their correlation with ovarian cancer stem cell markers." (PMID 37511212, 2023). "In conclusion, we reported for the first time, to the best of our knowledge, a prognostic role of AhRR and PPP1R3C expression in serous ovarian cancer." (PMID 37511212, 2023). "In a previous work, we identified a potential prognostic role of AhRR and PPP1R3C expression in serous ovarian cancer, starting from a detailed bioinformatics analysis of copy number gain arising in CSCs by array comparative genomic hybridization (array-CGH) analysis." (PMID 39596687, 2024).
diabetes (1 paper, 2018). "Importantly, Ide, Ppp1r3c, and Bad are located in Niddm1b, a diabetes susceptibility QTL which primarily affects insulin action and insulin-stimulated glucose transport." (PMID 30687391, 2018). "Therefore, the GK SAAC genes Ide, Ppp1r3c, Hdac9, Ghsr and Gckr with their specific mutations, may change the protein functions and improve insulin sensitivity in the prediabetes stage in GK rats and act as anti-diabetics in GK rats." (PMID 30687391, 2018). "Interestingly, dysfunction or inhibition of some specific genes such as Ide, Ppp1r3c, Hdac9, Ghsr and Gckr can improve insulin sensitivity to varying degrees in pre-diabetes period in GK rats." (PMID 30687391, 2018).
dilated cardiomyopathy (1 paper, 2021). Cardiomyopathy which is characterized by dilation and contractile dysfunction of the left and right ventricles. "LPIN1, PPP1R3C, PTPN1, CREM, and NR0B2 were identified as the main effectors in metabolism dysregulation in the remote zone and were found differentially expressed also in the myocardium of patients with ischemic and/or dilated cardiomyopathy." (PMID 34722683, 2021).
Encephalopathy (1 paper, 2009). Encephalopathy is a term that means brain disease, damage, or malfunction. "Expression of PPP1R3C has been associated with encephalopathy." (PMID 19216742, 2009).
Hepatic steatosis (1 paper, 2022). Steatosis is a term used to denote lipid accumulation within hepatocytes. "An interaction network based on DELs and differential genes (DEGs) suggested that QGD inhibited hepatic steatosis mainly by reducing hepatic insulin resistance and triglyceride biosynthesis via the PPP1R3C/SIK1/CRTC2 and PPP1R3C/SIK1/SREBP1 signal axis, respectively." (PMID 36452137, 2022).
Lafora disease (1 paper, 2014). Lafora disease (LD) is a rare, inherited, severe, progressive myoclonic epilepsy characterized by myoclonus and/or generalized seizures, visual hallucinations (partial occipital seizures), and progressive neurological decline. "A study of a similar protein, PPP1R3C, identified one missense mutation that may lead to a mild phenotype in Lafora disease—a teenage onset epilepsy disorder." (PMID 24795746, 2014).
liver cancer (1 paper, 2016). An epithelial or non-epithelial malignant neoplasm that arises from the liver. "Protein target to glycogen subunit PPP1R3C (PTG) protects liver cancer cells in the absence of glucose via regulation of oxidative stress and autophagy, whereas silencing PPP1R3C further promotes cytotoxicity." (PMID 26882899, 2016).
osteoporosis (1 paper, 2024). A condition of reduced bone mass, with decreased cortical thickness and a decrease in the number and size of the trabeculae of cancellous bone (but normal chemical composition), resulting in increased fracture incidence. "B4GALT4, ADH4, ACAD11, B4GALT2, and PPP1R3C may be valuable biomarkers for the development of osteoporosis." (PMID 38589566, 2024). "Thus, we propose that B4GALT4, ADH4, ACAD11, B4GALT2, and PPP1R3C are involved in the development of osteoporosis, potentially by modulating metabolic pathways." (PMID 38589566, 2024). "Our study performed a comprehensive analysis of important EMGs in osteoporosis and developed a diagnosis signature consisting 5 EMGs, including B4GALT4, ADH4, ACAD11, B4GALT2, and PPP1R3C with a relative higher AUC." (PMID 38589566, 2024). "Overall, this study constructed a model that can predict the incidence of osteoporosis and identified B4GALT4, ADH4, ACAD11, B4GALT2, and PPP1R3C as potential biomarkers for osteoporosis development." (PMID 38589566, 2024).
ovarian carcinoma (1 paper, 2023). A malignant neoplasm originating from the surface ovarian epithelium. "On top of that, the positive correlation between AhRR and PPP1R3C expression and ovarian cancer stemness markers’ expressions suggest a potential role in cancer stem cells, and reinforces their use as prognostic markers." (PMID 37511212, 2023). "We also demonstrated that increased AhRR and PPP1R3C expression was maintained in some CSCs subpopulations, suggesting their possible role in ovarian cancer." (PMID 37511212, 2023). "Bioinformatic analyses of genes involved in copy number gains revealed that AhRR and PPP1R3C expression negatively correlated with ovarian cancer patients’ overall and progression-free survival." (PMID 37511212, 2023). "To better analyze AhRR and PPP1R3C’s role in treatment responses, we investigated whether AhRR and PPP1R3C expression also correlates with ovarian cancer patients’ progression-free survival (PFS)." (PMID 37511212, 2023). "Furthermore, it has been previously reported that higher cancer stemness marker expressions were related to worse PFS in ovarian cancer patients, thus strengthening the potential for AhRR and PPP1R3C involvement in cancer stem cell regulation." (PMID 37511212, 2023). "Altogether, these data may suggest a potential prognostic role of AhRR and PPP1R3C, independent from chemotherapy treatment, in ovarian cancer." (PMID 37511212, 2023). "However, since the role of GALNT10 in ovarian cancer had already been reported, we focused our attention on AhRR and PPP1R3C." (PMID 37511212, 2023). "A deeper database analysis of genes involved in copy number gains revealed three genes whose expression negatively correlates with ovarian cancer patients’ overall survival in all tested datasets: AhRR, GALNT10, and PPP1R3C." (PMID 37511212, 2023). "Interestingly, AhRR and PPP1R3C expression significantly correlates with stemness markers’ (ALDH1A1, CD44, ABCG2, NANOG) expressions in ovarian cancer tissues (p < 0.01)." (PMID 37511212, 2023). "Furthermore, AhRR and PPP1R3C’s increased expression was maintained in some CSC subpopulations, reinforcing their potential role in ovarian cancer." (PMID 37511212, 2023). "To date, no data are reported about the potential role of PPP1R3C in ovarian cancer." (PMID 37511212, 2023).
renal cell carcinoma (1 paper, 2023). "On the other hand, in renal cell carcinoma, PPP1R3C is overexpressed and seems to be a cancer promoter." (PMID 37511212, 2023).
type 2 diabetes (1 paper, 2025). "PPP1R3C was the only DEG that appeared in all three fibre types and was consistently relatively more highly expressed in the untrained leg in the controls compared to the untrained leg in type 2 diabetes." (PMID 40413649, 2025).
tumor (14 papers, 2014 to 2024). "IRS2 and PPP1R3C, are involved in glycogen synthesis, and are among the downregulated genes in monosomy 3 tumours; both had a lower expression in UMs with epithelioid cells in a study performed on UMs using data from the TCGA." (PMID 37240204, 2023). "Tumors with the largest basal diameter above 13 mm exhibited a decline in BAP1, EPM2A, GYG1, GYG2, and PPP1R3C levels, whereas only EPM2A was negatively associated with an increased tumor thickness." (PMID 32751097, 2020). "Tumor necrosis was negatively correlated with the levels of PPP1R3C." (PMID 32751097, 2020). "Four tumor-related genes (NR4A3, CD74, PPP1R3C, and ANKRD1) with high differential expression were selected, and the GeneMANIA database was used to generate a protein–protein interaction (PPI) network diagram." (PMID 39474111, 2024). "The results showed that HK2, PGM1, PPP1R3C, GYS1, and G6PD were significantly up-regulated in ccRCC tumor tissues." (PMID 34522206, 2021). "Four genes, PPP1R3C, PHF21B, TPM1 and PPP1R14A, were highly downregulated in the tumor tissues compared with the normal tissues." (PMID 25789025, 2015). "Methylation status of PPP1R3C and EFHD1 was compared with other clinicopathological factors including sex, age, tumor stage, and tumor locations." (PMID 24861485, 2014). "In good agreement with these previous observation, methylation of PPP1R3C and EFHD1 in plasma DNA samples were detected commonly in CRC patients, regardless of sex, age, or tumor location." (PMID 24861485, 2014).
cancer (8 papers, 2017 to 2025). A tumor composed of atypical neoplastic, often pleomorphic cells that invade other tissues. "As a hypermethylated gene in CRC, PPP1R3C is thought to play a critical role in cancer cell growth, potentially in association with glucose levels." (PMID 40263288, 2025). "As primarily identified and characterized for aberrant metabolism during cancer, the carbohydrate-binding protein Ppp1r3c may be sensitive to CBD treatment." (PMID 40979532, 2025). "To investigate whether AhRR and PPP1R3C expression correlates with a worse outcome of patients in other cancers, we analyzed all TCGA datasets using GEPIA2 web server (accessed on 5 May 2023)." (PMID 37511212, 2023). "Based on these results, we examined TCGA dataset using GEPIA2 web server to determine whether the expression of AhRR and PPP1R3C correlates with the expression of cancer stem cells markers." (PMID 37511212, 2023). "Finally, AhRR and PPP1R3C’s correlation with patients’ worse OS was identified in other cancers." (PMID 37511212, 2023). "Analyzing gene expression and prognostic value in TCGA-COAD, we found that TCMM40L, SLC8A1, PPP1R3C, P2RX1 and HMX2 were significantly downregulated in cancer tissues." (PMID 40263288, 2025).
PPP1R3C also shares sentences with these, for which no sentence is quoted: Glucose intolerance (2 papers); prostate carcinoma (2); chromophobe renal cell carcinoma (1); colorectal adenoma (1); gastric carcinoma (1); glioblastoma (1); glioma (1); Hyperinsulinemia (1); metabolic disease (1); neuroblastoma (1); non-alcoholic fatty liver disease (1); prediabetes (1); sarcoma (1); uveal melanoma (1).